ZNF705G (zinc finger protein 705G)
Description:
May be involved in transcriptional regulation.
Tractability: No criterion of Open Targets' tractability assessment is met for any kind of drug.
Gene: Protein-coding gene on chromosome 8 (7,355,517 to 7,385,558, reverse strand). Ensembl gene ENSG00000215372.
Subcellular location: Nucleus
Pathways (Reactome):
Gene expression (Transcription): Generic Transcription Pathway
Gene Ontology:
Molecular function: DNA-binding transcription factor activity, RNA polymerase II-specific; RNA polymerase II transcription regulatory region sequence-specific DNA binding; sequence-specific double-stranded DNA binding
Biological process: regulation of transcription by RNA polymerase II; regulation of DNA-templated transcription
Cellular component: nucleus
Genetic constraint (gnomAD): Loss-of-function variants: 28 observed, 19.5 expected, observed/expected ratio (o/e) 1.44, 90% interval 1.06 to 1.87. The synonymous counts are far from expectation, so gnomAD's model fits this gene poorly and the ratio says little. Missense variants: 457 observed, 294.41 expected, observed/expected ratio (o/e) 1.55, 90% interval 1.44 to 1.68. Synonymous variants: 146 observed, 101.73 expected, observed/expected ratio (o/e) 1.44, 90% interval 1.25 to 1.65.
Homologues: Orthologues: mouse Zfp78 (34% identical), Drosophila melanogaster CG3281 (22% identical), Drosophila melanogaster CG2712 (20% identical), Drosophila melanogaster Phs (18% identical). Paralogues in human: ZNF705A (95% identical), ZNF705D (93% identical), ZNF705B (92% identical), ZNF596 (53% identical), ZFP90 (42% identical), ZNF555 (37% identical), ZNF266 (36% identical), ZNF805 (36% identical), ZNF599 (36% identical), ZFP69B (35% identical), ZNF614 (35% identical), ZNF264 (35% identical), and 50 more.